CDK8 (cyclin dependent kinase 8)
Diseases named in the same sentence as CDK8 in open-access papers (continued):
Sharing a sentence is not in itself a finding about the gene and the disease.
HIV-1 infection (1 paper, 2023). The type species of lentivirus and the etiologic agent of acquired immunodeficiency syndrome (AIDS). "Relating to this, we note that it was previously reported that knockdown of CDK8 and/or CDK19 does not affect HIV-1 infection in HeLa cells, where dCA has an inhibitory effect." (PMID 37671866, 2023).
infertile (1 paper, 2025). "As CDK8 iKO in our model is ubiquitous, infertility could be caused by decrease of LH level due to improper regulation in the brain." (PMID 40172945, 2025). "These experiments showed that both CDK8 iKO and iDKO are infertile, and the cause of CDK8 iKO infertility is likely to be the lack of sexual activity." (PMID 40172945, 2025).
Insulin resistance (1 paper, 2015). Increased resistance towards insulin, that is, diminished effectiveness of insulin in reducing blood glucose levels. "Thus, our results suggest that mTORC1 activation in NAFLD and insulin resistance results in down-regulation of the CDK8-CycC complex and elevation of lipogenic protein expression." (PMID 26042770, 2015). "In this study, using genetic and aging mouse models of insulin resistance and NAFLD, we show that mTORC1-dependent down-regulation of the CDK8-CycC complex plays a role in the persistent activation of de novo lipogenesis." (PMID 26042770, 2015).
Intellectual disability (1 paper, 2024). "Patients harboring missense mutations in either CDK8 or CDK19 present with a range of clinical features, including neurodevelopmental defects, variable intellectual disability, hypotonia, and facial dysmorphology." (PMID 38637532, 2024).
intestinal tumor (1 paper, 2021). "In contrast, CDK8 deletion in the ApcMin intestinal tumor model led to shortened survival and increased tumor burden." (PMID 33686962, 2021).
invasive breast carcinoma (1 paper, 2021). A carcinoma that infiltrates the breast parenchyma. "Besides, CDK8 drives the expression of matrix metalloproteinase Mmp9, which contributes to the invasive character of several cancer cell types and regulates Ccl2 in TNBC cells, which has been found overexpressed in invasive breast cancers and is suggested to support metastasis." (PMID 34689158, 2021).
ischemia (1 paper, 2025). A hypoperfusion of the BLOOD through an organ or tissue caused by a PATHOLOGIC CONSTRICTION or obstruction of its BLOOD VESSELS, or an absence of BLOOD CIRCULATION. "In all stromal cells combined at 7dpf, DEG analysis demonstrated a 2.5-fold increase (Padj =5.90e-303) in Cdk8 expression in Ischemia compared to Intact conditions." (PMID 40470203, 2025).
latent infections (1 paper, 2023). "Beyond assessing the ratio of productive versus latent infections, we took a closer examination of the effect of CDK8 KO on LTR-driven BFP expression." (PMID 37671866, 2023).
lymph node metastasis (1 paper, 2019). "MiR-101 induces LSCC cells apoptosis via targeting CDK8, and is dramatically reduced in LSCC tissues and related to clinical stages, T stages, lymph node metastasis, and poor prognosis." (PMID 31801947, 2019).
metastatic cancers (1 paper, 2015). A carcinoma which has spread from the original site of growth to another anatomic site. "Genes in the CMCG group (CDK4, CDK6, CDK8, GSK3B) had the most frequent copy number alterations in 86% of the primary and 65% of the metastatic cancers." (PMID 26420498, 2015).
metastatic melanoma (1 paper, 2024). A melanoma that has spread from its primary site to another anatomic site. "In addition, CDK8 is associated with G2/M transformation, and loss of CDK8 significantly reduces G2/M blockade-mediated proliferation in metastatic melanoma cell lines." (PMID 38606172, 2024).
oral squamous cell carcinomas (1 paper, 2024). "However, the role of circ-CDK8 in regulating ferroptosis, migration, and invasion of oral squamous cell carcinoma (OSCC) remains unknown." (PMID 39170701, 2024).
parasitic infections (1 paper, 2023). "Interestingly, secretory lineage hyperplasia occurs upon parasitic infections and is mediated by pro‐inflammatory cytokines, while CDK8 and CDK19 potentiate NFκB‐mediated pro‐inflammatory transcription and limit production of anti‐inflammatory cytokines." (PMID 36545778, 2023).
Parkinsonism (1 paper, 2024). Characteristic neurologic anomaly resulting from degeneration of dopamine-generating cells in the substantia nigra, a region of the midbrain, characterized clinically by shaking, rigidity, slowness of movement and difficulty with walking and gait. "Here, the authors examine Drosophila Cdk8/CDK19 function in mitochondrial fission and uncover a role phosphorylating Drp1 in the cytoplasm and show overexpression suppresses a Parkinson’s disease model." (PMID 38637532, 2024).
pituitary adenomas (1 paper, 2022). "This case-control study revealed an increased frequency of the CDK8 rs17083838 minor allele (A allele) in patients diagnosed with sporadic pituitary adenomas." (PMID 36233050, 2022). "The CDK8 rs17083838 minor allele (A allele) was significantly associated with overall sporadic pituitary adenomas under an additive (odds ratio (OR) 1.73, 95% confidence interval (CI) 1.19–2.50, p = 0.004) and dominant (OR 1.82, 95% CI 1.24–2.68, p = 0.002) inheritance model." (PMID 36233050, 2022). "The aim of this study was to investigate whether the NEBL rs2359536, PCDH15 rs10763170 and CDK8 rs17083838 SNPs are associated with the susceptibility to sporadic pituitary adenomas in the Portuguese population." (PMID 36233050, 2022). "The CDK8 rs17083838 minor allele (A allele) was significantly associated with sporadic pituitary adenomas, under an additive (odds ratio (OR) 1.73, 95% confidence interval (CI) 1.19–2.50, p = 0.004) and dominant (OR 1.82, 95% CI 1.24–2.68, p = 0.002) inheritance model." (PMID 36233050, 2022). "Three common variants at the NEBL (rs2359536), PCDH15 (rs10763170) and CDK8 (rs17083838) loci were previously associated with sporadic pituitary adenomas in the Han Chinese population, but these findings have not yet been replicated in any other population." (PMID 36233050, 2022). "In conclusion, our data suggest that the CDK8 rs17083838 variant, and possibly the PCDH15 rs10763170 variant, may increase susceptibility to sporadic pituitary adenomas in the Portuguese population." (PMID 36233050, 2022).
pituitary tumor (1 paper, 2022). A benign or malignant neoplasm affecting the pituitary gland. "Furthermore, studies of animal models of pituitary tumors have shown that several target genes of CDK8 are differentially expressed in these tumors, suggesting a role of this kinase in pituitary tumorigenesis." (PMID 36233050, 2022).
postmenopausal osteoporosis (1 paper, 2022). Metabolic disorder associated with fractures of the femoral neck, vertebrae, and distal forearm. "Collectively, our findings suggest that CDK8 may be considered an attractive treatable target against various metabolic bone diseases relevant to abnormal osteoclastogenesis, including age-related osteoporosis and postmenopausal osteoporosis." (PMID 35777359, 2022).
prostate adenocarcinoma (1 paper, 2019). "Furthermore, CDK8 and members of the mTOR pathway are correlated in a number of other cancers including thyroid carcinoma, thymoma, prostate adenocarcinoma, and liver hepatocellular carcinoma." (PMID 31628323, 2019).
teratoma (1 paper, 2021). A non-seminomatous germ cell tumor characterized by the presence of various tissues which correspond to the different germinal layers (endoderm, mesoderm, and ectoderm). "We report that long-term cultured CDK8/19i-naïve human PSCs retain the imprinting profile of their parental primed cells, and imprints are further retained upon differentiation in the context of teratoma formation." (PMID 33921436, 2021).
testicular cancer (1 paper, 2024). A primary or metastatic malignant neoplasm that affects the testis. "On the other hand, CDK8 is expressed at an intermediate level in the normal prostate and at a high level in the testes, but it is downregulated in both PCa and testicular cancers relative to their normal tissue counterparts." (PMID 38546787, 2024).
uterine cancer (1 paper, 2019). Primary or metastatic malignant neoplasm involving the uterine corpus and/or the cervix. "On the other hand, uterine cancers were unique in showing a high frequency of point mutations in CDK8/CDK19/CCNC." (PMID 31382571, 2019). "The impact of the CDK8/CDK19/CCNC mutations found in uterine cancers is unknown, but we note that uterine cancers were also one of the types that showed correlations between the expression of CDK8 and CDK19 and shorter survival." (PMID 31382571, 2019). "Among other cancer types with relatively frequent alterations of CDK8, CDK19, or CCNC, we note cancers of the uterus, where mutations of these genes were found more frequently than in the other cancer types; most of these were missense mutations of unknown significance." (PMID 31382571, 2019).
cancer (116 papers, 2015 to 2026). A tumor composed of atypical neoplastic, often pleomorphic cells that invade other tissues. "CDK8 encodes a cell cycle-related kinase, and is frequently overexpressed in various cancers and has been identified as a prognostic biomarker in CRC." (PMID 41075061, 2025). "This suggests that cancers associated with CDK8 are predominantly driven by transcriptional dysregulation." (PMID 40358161, 2025). "Given the crucial role of CDK8 in regulating gene transcription and cell signaling, its abnormal activity is associated with cancer." (PMID 38606172, 2024). "Particularly, in cancer, CDK8/19 act as oncogenes, and their overexpression has been associated with several types of cancer, such as breast, colorectal, and colon cancer." (PMID 37376593, 2023). "CDK8 is implicated in cancer cell de‐differentiation and helps to maintain stem cell pluripotency due to regulation of the Myc proto‐oncogene." (PMID 37718413, 2023). "The dual actions of the highly related kinases CDK8/CDK19 have led them to be implicated in cancer development as both drivers or suppressors of tumorigenesis." (PMID 37718413, 2023). "It is noteworthy to know that (CDK8) is upregulated in various cancers, and higher expression of this gene is associated with low surveillance of patients." (PMID 36132137, 2022). "The rs17083838 polymorphism is located in the first intron of the CDK8 gene, which is overexpressed in several cancers." (PMID 36233050, 2022). "An increased expression of CDK8 occurs in some types of cancer, while DNA damage is closely linked to the etiology of malignant diseases." (PMID 34444642, 2021). "We have found, however, that stratifying cancers by high and low mutation burden changes the correlation of CDK8 expression from shorter to longer survival." (PMID 31382571, 2019). "In recent years, dysregulation of Mediator kinase module proteins, including CDK8/19, has been implicated in the development of different human diseases, and in particular cancer." (PMID 30693281, 2018). "CDK8 has also been implicated in melanomagenesis, pancreatic cancer and associated with the cancer stem cell phenotype." (PMID 28147342, 2017). "On the other hand, mutations T196A and T196D have been demonstrated to enhance CDK8 activity, leading to anomalous cell proliferation and division, which could potentially facilitate the advancement and exacerbation of cancer." (PMID 38615023, 2024). "Cdk8 is an important enzyme that regulates the expression of genes in response to signals to which cells need to respond and which is produced by a gene that is frequently mutated in cancers." (PMID 37671866, 2023). "In contrast to CDK8, almost nothing is known about CDK19 roles in cancer, and whether it compensates for loss of CDK8 remains unknown." (PMID 36545778, 2023). "Cdk8 is a cyclin-dependent kinase implicated in cellular homeostasis and developmental programming, and it has been shown to regulate several signaling pathways that are crucial regulators of both embryonic stem cell pluripotency and cancer." (PMID 36292630, 2022). "Intriguingly, CDK8/19 loss produced broad effects in the cancer state compared with normal tissue." (PMID 36006697, 2022). "Here, we found that the lencRNA PRKDC-210 interacts with the CDK8 complex, resulting in transcriptional upregulation, which may be a major cause of abnormal gene expression in cancer." (PMID 36430260, 2022). "Notably, CDK8 was first linked to cancer when it was identified as an oncogene that is frequently amplified or overexpressed in CRC." (PMID 32596239, 2020). "Interestingly, BMP4 stimulates a YAP dependent increase in CDK8 which would also reduce junctional E-cadherin and contribute to cancer associated EMT." (PMID 33057364, 2020). "Notably, several subunits of the Mediator complex have been implicated in the pathogenesis of human diseases including cancer, for which most evidence has been obtained regarding the involvement of CDK8." (PMID 29568371, 2018).
cancer (continued). "Indeed, Cdk8 overexpression has been associated with poor prognosis in cancer patients." (PMID 30621145, 2019). "The targeting of cyclin dependent kinase 8 (CDK8) as a potential strategy for cancer treatment has been of interest since the identification of CDK8 as an oncogene product." (PMID 41596544, 2026). "Our previous study revealed that CDK8 inhibition attenuated the TGFβ-induced EMT process in cancer metastasis." (PMID 39781457, 2025). "As part of the mediator complex, CDK8 activates key transcription factors, including those within the Wnt/β-catenin pathway, making it a critical target for disrupting multiple cancer-driving pathways simultaneously." (PMID 40699862, 2025). "As a result, researchers have focused a great deal of attention on CDK8, and several CDK8 inhibitors have been identified as promising cancer therapeutics." (PMID 40699862, 2025). "The role of CDK8 in the initiation and spread of cancer has been demonstrated in numerous investigations." (PMID 40361480, 2025). "According to recent research, CDK8 is essential for several signaling pathways, including the Wnt/β-catenin pathways that promote the spread of cancer cells." (PMID 40699862, 2025). "As an important factor in transcriptional regulation, CDK8 dysregulation is closely related to cancer development." (PMID 39800748, 2025). "In this review, we first elucidate the role of CDK8 in the transcription process, and then explore its biological functions in cancer, including the cycle change, invasion and migration, tumor metabolism, DNA damage and immune." (PMID 38606172, 2024). "Theoretical studies were conducted on the human CDK8–CycC complex in order to gain a greater understanding of the binding of CycC to CDK8, which is an important target in cancer therapy." (PMID 38791449, 2024). "This comprehensive review delves into the intricate involvement of CDK8 in transcription-related processes, as well as its role in signaling pathways related to tumorigenesis, with a focus on its critical part in driving cancer progression." (PMID 38606172, 2024). "The analysis of Mediator kinase expression in clinical cancers, together with prior reports, shows that CDK8 is downregulated and CDK19 upregulated in primary PCa, which we can now explain by the regulation of CDK8 and CDK19 expression by androgen signaling." (PMID 38546787, 2024). "We found that circ-CDK8 expression was significantly higher in cancer tissues and OSCC cells than in normal tissue and HOK cells." (PMID 39170701, 2024). "CDK8 has emerged as a significant target for drug therapy in various cancers, including melanoma, breast, prostate, and pancreatic cancers." (PMID 38615023, 2024). "Cyclin-dependent kinase 8 (CDK8) has emerged as a promising target for inhibiting cancer cell function, intensifying efforts towards the development of CDK8 inhibitors as potential cancer therapeutics." (PMID 38615023, 2024). "Overexpression of CDK8 has been demonstrated in various types of cancer, including colon cancer, breast cancer, glioblastoma, and hepatocellular carcinoma, making it a potential therapeutic target." (PMID 39574899, 2024). "In this way, CDK8/cyclin C can keep cancer cells alive by promoting replication stress response of cancer cells and thus reducing DNA damage." (PMID 38606172, 2024). "al. in the paper “Cyclin-Dependent Kinase 8: A New Hope in Targeted Cancer Therapy?” focus on cyclin-dependent kinase 8 (CDK8), which is a protein that plays a role in regulating gene expression and has been implicated in various cancers." (PMID 38615023, 2024). "In contrast, CDK8 overexpression produces tumor suppressive effects of cancers promoted by Notch or EGFR signaling." (PMID 37671866, 2023). "CDK8 is overexpressed in a variety of cancers, including breast and colorectal carcinomas, and malignant melanomas, where expression is associated with tumor progression." (PMID 37671866, 2023).